PTGIR (prostaglandin I2 receptor)
Description:
Receptor for prostacyclin (prostaglandin I2 or PGI2). The activity of this receptor is mediated by G(s) proteins which activate adenylate cyclase.
Synonyms: PRIPR; IP
Tractability: Small molecule: an approved drug acts on it; a structure with a bound ligand is known; a high-quality ligand is known; it belongs to a druggable protein family. Antibody: its Gene Ontology location is reachable by antibodies, with high confidence; UniProt places it where antibodies can reach, with medium confidence; UniProt predicts a signal peptide or a membrane-spanning region. PROTAC: a small molecule that binds it is known.
Target class: Lipid-like ligand receptor (family A GPCR); Membrane receptor; Prostanoid receptor; Small molecule receptor (family A GPCR); Family A G protein-coupled receptor
Chemical probes: FK-788, ILOPROST (high quality)
Safety:
Unwanted effects reported when the protein is acted on. In parentheses: how it was acted on, where the effect was seen, and who reports it.
aspirin-intolerant asthma (source: ClinPGx)
Gene: Protein-coding gene on chromosome 19 (46,618,550 to 46,625,534, reverse strand). Ensembl gene ENSG00000160013.
Subcellular location: Cell membrane
Pathways (Reactome):
Signal Transduction: G alpha (s) signalling events; Prostanoid ligand receptors
Hemostasis: Prostacyclin signalling through prostacyclin receptor
Gene Ontology:
Molecular function: protein binding; guanyl-nucleotide exchange factor activity; prostacyclin receptor activity; G protein-coupled receptor activity
Biological process: adenylate cyclase-activating G protein-coupled receptor signaling pathway; negative regulation of smooth muscle cell proliferation; cell-cell signaling; G protein-coupled receptor signaling pathway, coupled to cyclic nucleotide second messenger; inflammatory response; negative regulation of platelet-derived growth factor receptor signaling pathway; positive regulation of cytosolic calcium ion concentration; G protein-coupled receptor signaling pathway; vasodilation
Cellular component: cytosol; plasma membrane; membrane
Genetic constraint (gnomAD): Loss-of-function variants: 17 observed, 12.38 expected, observed/expected ratio (o/e) 1.37, 90% interval 0.93 to 1.88. The synonymous counts are far from expectation, so gnomAD's model fits this gene poorly and the ratio says little. Missense variants: 532 observed, 479.31 expected, observed/expected ratio (o/e) 1.11, 90% interval 1.03 to 1.19. Synonymous variants: 274 observed, 218.28 expected, observed/expected ratio (o/e) 1.26, 90% interval 1.14 to 1.39.
Homologues: Orthologues: chimpanzee PTGIR (99% identical), macaque PTGIR (97% identical), pig PTGIR (85% identical), dog PTGIR (83% identical), guinea pig PTGIR (83% identical), rabbit PTGIR (82% identical), rat Ptgir (79% identical), mouse Ptgir (79% identical), tropical clawed frog ptgir (50% identical), zebrafish ptgir (45% identical). Paralogues in human: PTGER2 (36% identical), PTGDR (35% identical), PTGER4 (33% identical), PTGER3 (25% identical), TBXA2R (24% identical), PTGER1 (24% identical), PTGFR (21% identical).
Diseases named in the same sentence as PTGIR in open-access papers:
PTGIR is named in the same sentence as 47 diseases in open-access papers, as found by Europe PMC text mining. Sharing a sentence is not in itself a finding about the gene and the disease. The quoted sentences say what the papers report.
atherosclerosis (5 papers, 2009 to 2025). A disease characterized by the build-up of fatty material and calcium deposition in the arterial wall resulting in partial or complete occlusion of the arterial lumen. "PTGIR gene polymorphisms are a useful model for studying how PGI2 signalling may cause atherosclerosis and thrombotic disorders in humans." (PMID 41516038, 2025). "Interestingly, we observed that the immunoinflammatory biological processes and atherosclerosis deterioration-related pathways shared some common genes, including LYN, PTGIR, F11R, and C3AR1." (PMID 34095251, 2021).
breast carcinoma (3 papers, 2015 to 2024). "As a result, we characterized F11R and PTGIR as novel membrane markers in CTCs of mesenchymal state in breast cancer." (PMID 38375422, 2024). "As a result, we proposed F11R and PTGIR as new membrane markers for detecting CTCs of mesenchymal state in breast cancer." (PMID 38375422, 2024). "By exploring genes commonly identified in the both analyses, F11R and PTGIR were characterized as membrane markers in CTCs of mesenchymal state in breast cancer, which were evaluated by enriched terms, literature evidence, and relevant molecular pathways." (PMID 38375422, 2024). "PTGIR is associated with NSCLC and AATK is associated with other cancer types such as malignant glioma, lung and breast cancers." (PMID 26541675, 2015).
oropharyngeal cancer (3 papers, 2020 to 2024). Carcinoma, predominantly squamous cell, arising from the epithelial cells of the oropharynx. "Additionally, it has been observed that the downregulated expression of PTGDR2, PTGDR1, and PTGIR genes was associated with a poorer prognosis in oropharyngeal cancer patients, and all three can be used to screen HPV-ctDNA-negative HPV oropharyngeal cancer patients." (PMID 38704736, 2024). "Additional analysis including only patients with oropharyngeal cancer (n = 79) revealed a shorter DFS for methylated than for unmethylated PTGIR and TBXA2R (log-rank test, P = 0.003 and P = 0.009, respectively)." (PMID 31969157, 2020). "Methylation statuses of the PTGIR and TBXA2R promoters were positively correlated with recurrence in patients with oropharyngeal cancer (OR, 2.99; 95% CI 1.13–7.92; P = 0.028 and OR, 5.21; 95% CI 1.63–16.67; P = 0.006, respectively)." (PMID 31969157, 2020). "Methylation of the PTGIR and TBXA2R promoters was positively correlated with recurrence in oropharyngeal cancer (P = 0.028 and P = 0.006, respectively)." (PMID 31969157, 2020).
asthma (2 papers, 2018 to 2024). "Among them, 4 genes validated by ROC curve analysis with AUC > 0.70 revealed potential diagnostic values for asthma, including C3, PTGIR, CX3CL1 and PTHLH." (PMID 38640283, 2024). "Among them, C3, PTGIR, CX3CL1, and PTHLH has important clinical diagnostic value and are correlated with infiltration of multiple immune cell types in asthma." (PMID 38640283, 2024). "C3, PTGIR, CX3CL1, and PTHLH have important clinical diagnostic values and are correlated with infiltration of multiple immune cell types in asthma." (PMID 38640283, 2024). "To further validate our findings, we analyzed the correlation between 4 hub genes (C3, PTGIR, CX3CL1, and PTHLH) and immune cell infiltration in asthma, This result indicates that C3, PTGIR, CX3CL1, and PTHLH expression were significantly correlated with the infiltration of immune cells." (PMID 38640283, 2024).
colitis (2 papers, 2023 to 2025). Inflammation of the colon. "Overall, these data indicate that the antifibrotic effect of the PTGIR agonist in both acute and chronic colitis murine models is correlated with reduced YAP stromal expression, which suggests that PGI2-PTGIR activation may prevent intestinal fibrosis by downregulating YAP." (PMID 40390655, 2025). "Consistently, IHC analysis revealed elevated expression of PTGIR in the stroma, which was downregulated in BPS-treated mice, probably due to alleviated intestinal inflammation in this colitis model." (PMID 40390655, 2025).
migraine (2 papers, 2017 to 2018). "In our previous paper, we reported that elevated expression of Prostaglandin I2 receptor (PTGIR) in migraineurs, compared to healthy controls, may have a critical role in triggering migraine attacks." (PMID 30627197, 2018).
ovarian carcinoma (2 papers, 2024). A malignant neoplasm originating from the surface ovarian epithelium. "In ovarian cancer, it was driven by PGI2/PTGIR to induce pro-tumor and immunosuppression." (PMID 38363409, 2024).
Sepsis (2 papers, 2021 to 2025). Sepsis is defined as life-threatening organ dysfunction caused by a dysregulated host response to infection. "Sepsis increased coronary arteries expressions of nitric oxide synthases, prostaglandin I2 receptor, and prostaglandin F2α receptor." (PMID 34925058, 2021). "Interestingly, PTGIR and esculin were identified as each other’s 1st compounds, underscoring their synergistic role in modulating the immune response in sepsis." (PMID 40761792, 2025).
acute monocytic leukemia (1 paper, 2022). Acute monoblastic leukemia (AML-M5), is one of the most common subtypes of acute myeloid leukemia (AML) that is either comprised of more than 80% of monoblasts (AML-M5a) or 30-80% monoblasts with (pro)monocytic differentiation (AML-M5b). "Although THP-1 are widely used as a model of human monocytes, they derive from a patient with acute monocytic leukemia, thus to validate the PG-CP connection in non-leukemic cells, we studied the impact of the PTGIR agonist on the expression of the CP genes in hiPSC-derived monocytes." (PMID 36155972, 2022).
Chronic colitis (1 paper, 2025). A chronic inflammatory disease of the large intestine (colon, cecum and rectum). "Primary intestinal fibroblasts and a chronic colitis model were used for assessing the efficacy of a PTGIR agonist in combating fibrosis." (PMID 40390655, 2025). "In the chronic colitis murine model, the mice were fed drinking water containing 2% DSS for 3 cycles and treated with BPS before the third cycle of DSS induction to further explore the antifibrotic effect of the PTGIR agonist in vivo." (PMID 40390655, 2025).
hypothyroidism (1 paper, 2021). Abnormally low levels of thyroid hormone. "In our study, we also demonstrated a lower level of PTGIR in the group of animals with induced hypothyroidism." (PMID 34573602, 2021).
migraine headache (1 paper, 2018). "In conclusion, our data support the hypothesis that mutations in PTGIR gene, particularly the mutation we described, should be considered even in cases of migraine headache." (PMID 30627197, 2018). "Thus, in this study, the direct PCR amplification and sequencing of coding and noncoding exons and exon-intron boundaries of PTGIR gene was examined in patients with migraine headache and healthy controls." (PMID 30627197, 2018).
renal cell cancer (1 paper, 2022). "The prostaglandin I2 receptor (PTGIR) was the most upregulated gene and has already been associated with mouse TEC in renal cell cancer." (PMID 35717322, 2022).
type 1 von Willebrand disease (1 paper, 2015). "Platelet G protein-coupled receptor genes P2RY1, F2R, F2RL3, TBXA2R and PTGIR were sequenced in 146 index cases with type 1 von Willebrand disease and the potential effects of identified single nucleotide variations were assessed using in silico methods and heterologous expression analysis." (PMID 26630678, 2015).
type 1 VWD (1 paper, 2015). "We have identified seven heterozygous SNVs affecting F2R, F2RL3, TBXA2R and PTGIR in 8 of 146 patients with a historical diagnosis of type 1 VWD who were enrolled in the MCMDM-1VWD study." (PMID 26630678, 2015).
uterine cancer (1 paper, 2022). Primary or metastatic malignant neoplasm involving the uterine corpus and/or the cervix. "Models of regulation of PTGIS and PTGIR gene expression in lung and uterine cancers were suggested." (PMID 35453789, 2022).
tumor (8 papers, 2011 to 2025). "PTGIS is highly expressed by cancer-associated fibroblasts (CAF), concomitant with elevated PGI2 synthesis, whereas tumor-associated macrophages (TAM) exhibit the highest expression of its surface receptor (PTGIR)." (PMID 36551640, 2022). "Down-regulation of the PTGIS and PTGIR genes in eight different tumors may be associated with a more aggressive tumor phenotype due to the abolishment of prostacyclin’s tumor-suppressive effects." (PMID 35453789, 2022). "Other pairs of co-expressed genes encoding prostanoid receptors were as follows: PTGIR-PTGER2, r = 0.72 − 0.75, TGCT tumor; PTGER4-PTGER2, 0.68–0.78, SKCM tumor; PTGDR-PTGER2, r = 0.66 − 0.74, SKCM tumor; PTGDR-PTGER3, 0.59–0.67, PAAD tumor." (PMID 35453789, 2022). "Models of CBR1 and PTGIR post-translational regulation models were mediated via neddylation and ubiquitination/deubiquitination as well as phosphorylation depending on tumor types." (PMID 35453789, 2022). "Furthermore, conditioned medium from PGI2-agonist-treated TAM promoted tumor adhesion to mesothelial cells and migration in a PTGIR-dependent manner, and PTGIR activation induced the expression of metastasis-associated and pro-angiogenic genes." (PMID 36551640, 2022). "We chose primary tumor cells (ascTU) for this purpose, which express very low levels of PTGIS and PTGIR, so that autocrine effects are negligible." (PMID 36551640, 2022). "Taken together, our study identifies a PGI2/PTGIR-driven crosstalk between CAF, TAM and tumor cells, promoting immune suppression and a pro-metastatic environment." (PMID 36551640, 2022). "A major target of their products seem to be TAMs, which express considerable higher levels of the PGE2 and PGI2 receptor genes PTGER2, PTGER4, and PTGIR with the exception of PTGER3 expressed only by a small subset of tumor cells." (PMID 27215396, 2016). "This released PGI2 binds to the PGI2 receptor (PTGIR) on ascitic TAMs, promoting their polarization toward an immunosuppressive and pro-tumor phenotype characterized by reduced phagocytic capacity; furthermore, secretion of immune-stimulated cytokines is diminished." (PMID 40453088, 2025). "The migration of primary tumor cells was significantly enhanced by the conditioned medium from MRE-269-treated compared to untreated TAM, which was partially blocked by the PTGIR antagonist CAY10449, suggesting an involvement of PTGIR signaling." (PMID 36551640, 2022). "Most of the transcriptomic signatures (without subgroup analysis) still show acceptable tumor specificity with the exception of the signature containing PTGDS, CBR3, PTGIR, PTGFR, PTGDR2, and PTGER3 genes in HNSC tumor, which is similar to other tumors (BRCA, CESC, LUAD, SARC, and UCES)." (PMID 35453789, 2022).
cancer (5 papers, 2015 to 2025). A tumor composed of atypical neoplastic, often pleomorphic cells that invade other tissues. "Previous studies have shown that the characterized two markers (F11R and PTGIR) are associated with cancer progression, epithelial-mesenchymal transition (EMT), or metastasis." (PMID 38375422, 2024). "If MAPK4 (TSS1500), HNRNPM, and PTGIR hypomethylation among smokers—what we observed—leads to greater protein expression, this could partially explain their increased risk for lung and heart diseases and several cancers." (PMID 35277542, 2022).
PTGIR also shares sentences with these, for which no sentence is quoted: pulmonary arterial hypertension (21 papers); diabetes (2); pulmonary hypertension (2); Achenbach syndrome (1); arteriosclerosis obliterans (1); atrial septal defect (1); Autoimmunity (1); cardiovascular disease (1); colorectal cancer (1); COVID-19 (1); Crohn disease (1); endothelial dysfunction (1); fibrosis (1); glioblastoma (1); haemolytic anaemia (1); heart diseases (1); heart failure (1); Hypertension (1); hypopharyngeal cancers (1); immune diseases (1); ischemic heart disease (1); laryngeal carcinoma (1); liver fibrosis (1); malignant glioma (1); Obesity (1); oral cancers (1); Stroke (1); thrombotic disorders (1); ulcers (1).